SNRPB (small nuclear ribonucleoprotein polypeptides B and B1)
Description:
Plays a role in pre-mRNA splicing as a core component of the spliceosomal U1, U2, U4 and U5 small nuclear ribonucleoproteins (snRNPs), the building blocks of the spliceosome. Component of both the pre-catalytic spliceosome B complex and activated spliceosome C complexes. As a component of the minor spliceosome, involved in the splicing of U12-type introns in pre-mRNAs. As part of the U7 snRNP it is involved in histone pre-mRNA 3'-end processing.
Synonyms: snRNP-B; Sm-B/B'; SmB/B'; COD; SNRPB1; SmB/SmB'; CCMS
Tractability: Small molecule: a structure with a bound ligand is known. PROTAC: ubiquitination databases record sites on it; its protein half-life has been measured.
Gene: Protein-coding gene on chromosome 20 (2,461,634 to 2,470,884, reverse strand). Ensembl gene ENSG00000125835.
Subcellular location: Cytoplasm, cytosol; Nucleus
Subcellular location (Human Protein Atlas): Nucleoplasm
Pathways (Reactome):
Metabolism of RNA: SLBP Dependent Processing of Replication-Dependent Histone Pre-mRNAs; SLBP independent Processing of Histone Pre-mRNAs; mRNA Polyadenylation; mRNA Splicing - Major Pathway; mRNA Splicing - Minor Pathway; snRNP Assembly
Disease: Dengue Virus-Host Interactions; SARS-CoV-2 modulates host translation machinery
Chromatin organization: CHD1 and CHD2 subfamily
Gene expression (Transcription): RNA Polymerase II Transcription Termination
Gene Ontology:
Molecular function: protein binding; RNA binding; telomerase RNA binding; snRNP binding; histone pre-mRNA DCP binding; U1 snRNP binding; U2 snRNP binding
Biological process: mRNA splicing, via spliceosome; protein methylation; spliceosomal snRNP assembly; 7-methylguanosine cap hypermethylation; negative regulation of mRNA splicing, via spliceosome; nuclear histone mRNA catabolic process; RNA splicing; spliceosomal complex assembly; spliceosomal tri-snRNP complex assembly; spliceosome conformational change to release U4 (or U4atac) and U1 (or U11); U2-type prespliceosome assembly
Cellular component: catalytic step 2 spliceosome; cytosol; methylosome; nucleoplasm; nucleus; post-mRNA release spliceosomal complex; post-spliceosomal complex; precatalytic spliceosome; SMN-Sm protein complex; spliceosomal complex; telomerase holoenzyme complex; U1 snRNP; U11/U12 snRNP; U12-type catalytic step 2 spliceosome; U12-type precatalytic spliceosome; U12-type spliceosomal complex; U2-type catalytic step 1 spliceosome; U2-type catalytic step 2 spliceosome; U2-type precatalytic spliceosome; U2-type spliceosomal complex; U4 snRNP; U4/U6 x U5 tri-snRNP complex; U7 snRNP; cytoplasm; small nuclear ribonucleoprotein complex; and 8 more
Genetic constraint (gnomAD): Loss-of-function variants: 2 observed, 19.43 expected, observed/expected ratio (o/e) 0.1, 90% interval 0.041 to 0.32. The upper end of that interval is the gene's LOEUF score, 0.32, which puts it in group 1 of 6, group 1 being the genes least tolerant of losing a copy. Missense variants: 159 observed, 250.24 expected, observed/expected ratio (o/e) 0.64, 90% interval 0.56 to 0.73. Synonymous variants: 98 observed, 89.44 expected, observed/expected ratio (o/e) 1.1, 90% interval 0.93 to 1.3.
Homologues: Orthologues: dog SNRPB (100% identical), guinea pig SNRPB (100% identical), rat Snrpb (100% identical), mouse Snrpb (99% identical), pig SNRPB (99% identical), macaque SNRPB (99% identical), zebrafish snrpb (94% identical), tropical clawed frog snrpb (94% identical), chimpanzee SNRPB (67% identical), Drosophila melanogaster SmB (58% identical), Caenorhabditis elegans snr-2 (39% identical). Paralogues in human: SNRPN (92% identical).
Diseases named in the same sentence as SNRPB in open-access papers:
SNRPB is named in the same sentence as 44 diseases in open-access papers, as found by Europe PMC text mining. Sharing a sentence is not in itself a finding about the gene and the disease. The quoted sentences say what the papers report.
Cerebro-costo-mandibular syndrome (11 papers, 2014 to 2026). Cerebro-costo-mandibular syndrome (CCMS) is characterized at birth by posterior rib gaps and orofacial anomalies reminiscent of Pierre Robin syndrome (see this term) that include palatal defects (short hard palate, absent soft palate, absent uvula), micrognathia and glossoptosis. "We present a unique case of an infant born with both a microduplication of 22q11.2 and SNRPB gene mutations suggestive of cerebro-costo-mandibular syndrome (CCMS)." (PMID 41727730, 2026). "Heterozygous variants of SNRPB, a core component of the five small ribonucleoprotein particles of the spliceosome, cause cerebrocostomandibular syndrome." (PMID 41283296, 2025). "Disease‐causing variant sequences within the PE of the human SNRPB gene (that encodes a splicing factor) lead to increased PE inclusion, thereby reducing SNRPB mRNA expression and causing cerebro‐costo‐mandibular syndrome." (PMID 41178187, 2025). "Loss of function of SNRPB is causally linked to cerebro-costo-mandibular syndrome (CCMS), a genetic disease characterized by bone defects." (PMID 39160274, 2024). "Mutations in SNRPB were shown to be linked to a rare genetic disease called Cerebro-costo-mandibular syndrome (CCMS)." (PMID 39160274, 2024). "Loss‐of‐function mutations of SNRPB in humans cause cerebro‐costo‐mandibular syndrome (CCMS) characterized by rib gaps, micrognathia, cleft palate, and scoliosis." (PMID 36058892, 2023). "Heterozygous mutations in SNRPB, an essential core component of the five small ribonucleoprotein particles of the spliceosome, are responsible for cerebrocostomandibular syndrome (CCMS)." (PMID 35593225, 2022). "Several groups have reported heterozygous mutations in SNRPB in patients with cerebrocostomandibular syndrome (CCMS; OMIM #117650)." (PMID 35593225, 2022). "These genes are associated with recognizable syndromes such as (acampomelic) campomelic dysplasia (SOX9), cerebro‐costo‐mandibular syndrome (SNRPB), SATB2‐associated syndrome (Glass syndrome, SATB2), Catel‐Manzke syndrome (TGDS), TARP syndrome (RBM10), and Stickler syndrome (COL2A1, COL11A1)." (PMID 41077824, 2026). "In addition to its essential role in splicing, mutations in SNRPB are known to cause cerebro-costo-mandibular syndrome." (PMID 27287018, 2016). "Importantly, non‐penetrance has also been previously documented for SF3B4 (Nager syndrome) and SNRPB (cerebro–costo–mandibular syndrome), indicating that it is not a novel observation for spliceosome genes." (PMID 41427026, 2025).
glioblastoma (6 papers, 2016 to 2022). The most malignant astrocytic tumor (WHO grade IV). "We found two independent data sets where SNRPB was knocked down in U251 glioblastoma cells or in HeLa cells." (PMID 34984976, 2022). "Numerous studies have revealed the critical role of SNRPB, a core component of spliceosome, in tumorigenesis, including cervical cancer, glioblastoma and non-small cell lung cancer." (PMID 36329787, 2022). "Recently, it has been reported that dysregulation of SNRPB is involved in human cancers, such as nonsmall cell lung cancer, glioblastoma and cervical cancer." (PMID 33289700, 2020).
lung cancer (5 papers, 2012 to 2024). A malignant neoplasm involving the lung. "SNRPB is upregulated in multiple cancers, including lung cancer, compared with corresponding normal tissues." (PMID 31511502, 2019). "A prognostic score based on the expression of ADAR2 and four additional RNA metabolism-related genes (MARS, RAE1, SNRPB and SNRPE) can stratify lung cancer patients into high and low risk groups for cancer death." (PMID 22876301, 2012). "Building on our findings that SNRPB co-expressed with RAB26 in NSCLC cell lines, we accessed the UALCAN26 and cBioPortal27 datasets to assess the relationship between expression of the SNRPB gene and RAB26 gene in clinical lung cancer samples." (PMID 31511502, 2019).
microcephaly (4 papers, 2020 to 2025). A congenital or acquired developmental disorder in which the circumference of the head is smaller than normal for the person's age and sex. "Loss of function of SNRPB underlies the rare genetic disease CCMS, which is characterized by severe bone deformations, microcephaly, rib defects and, micrognathia." (PMID 39160274, 2024).
cervical cancer (3 papers, 2020 to 2022). A primary or metastatic malignant neoplasm involving the cervix. "Also, SNRPB is highly expressed in cervical cancer, glioma, and hepatocellular cancer, which is a prognostic factor." (PMID 35356432, 2022).
ovarian carcinoma (3 papers, 2025). A malignant neoplasm originating from the surface ovarian epithelium. "A role for BRCA2 splice variants in BRCA2 wild-type ovarian cancer has been suggested by a recent study investigating the effect of the splicing factor small nuclear ribonucleoprotein B (SNRPB)." (PMID 40724944, 2025). "It provides further evidence that BRCA2 splicing may be regulated by factors outside the BRCA2 gene, and that a loss of coordinated splicing and BRCA2 expression by SNRPB depletion suppresses ovarian cancer cell proliferation and rescues chemotherapy response." (PMID 40724944, 2025). "SNRPB was found to be upregulated in ovarian cancer cells, promoted tumor growth, supported canonical BRCA2 splicing, and suppressed aberrant exon 3 skipping, thereby affecting the response to cisplatin." (PMID 40724944, 2025). "SNRPB knockdown inhibited ovarian cancer cell proliferation, downregulated DNA replication and HR genes, and promoted aberrant BRCA2 exon 3 skipping, leading to a loss of the PALB2 binding domain and further impairment of HR." (PMID 40724944, 2025). "Similarly, in ovarian cancer, SNRPB promoted tumor progression by regulating DNA replication and homologous recombination pathways." (PMID 40682115, 2025).
prostate carcinoma (3 papers, 2009 to 2022). A carcinoma that arises from epithelial cells of the prostate gland. "In prostate cancer, SNRPB was initially regarded as a metastasis suppressor gene, as its mRNA expression significantly decreased in metastasizing tumors compared to that in non-tumor tissue." (PMID 35281269, 2022). "In a mouse allograft model of prostate cancer (NE-10), SNRPB was identified as a candidate metastasis suppressor gene." (PMID 27287018, 2016). "With regard to RASSF2 and SNRPB, Goodzari and co-workers found evidence for a prostate cancer metastasis suppressor gene on the short arm of human chromosome 20." (PMID 19781100, 2009).
glioma (2 papers, 2019 to 2022). A benign or malignant brain and spinal cord tumor that arises from glial cells (astrocytes, oligodendrocytes, ependymal cells). "Regulatory network of splicing factors and prognostic splicing events were shown; suggesting hub splicing factors including SNRPB and CELF2 were participating in splicing regulatory in glioma." (PMID 31729991, 2019). "We also found SNRPB and CELF2 as hub splicing factors of prognostic splicing events, indicating that these splicing factors might be potential targets for glioma treatment." (PMID 31729991, 2019).
non-small cell lung carcinoma (2 papers, 2022 to 2025). A group of at least three distinct histological types of lung cancer, including non-small cell squamous cell carcinoma, adenocarcinoma, and large cell carcinoma. "Small nuclear ribonucleoprotein polypeptides B and B' (SNRPB) may regulate the tumorigenic potential of non-small cell lung cancer by modulating RAB26 expression, not by relying on RAB26's autophagic function." (PMID 40821113, 2025).
Autosomal dominant microcephaly (1 paper, 2020). "Among 141 protein coding genes within this deletion region, mutations only in SNRPB and CSNK2A1 have been reported to be associated with autosomal dominant microcephaly." (PMID 32863884, 2020).
brain tumors (1 paper, 2021). "Many oncogenic RBPs such as hnRNPH1, IGF2BP3, HuR, PTB, and SNRPB have been identified and characterized in the context of brain tumors." (PMID 35011618, 2021).
breast carcinoma (1 paper, 2012). "A rare polymorphism in the SNRPB gene has been associated with reduced risk of breast cancer in BRCA1 mutation carriers." (PMID 22876301, 2012).
COVID-19 (1 paper, 2025). A disease caused by infection with severe acute respiratory syndrome coronavirus 2. "Based on our results, we suggest that controlling high-severity-specific markers (FOS, CXCL8, HLA-A, JAK3, ICAM1, and H2BC4) and low-severity-specific markers (IL1B, CD3D, CD4, CCL5, and SNRPB) may prevent COVID-19 progression." (PMID 41155463, 2025).
endometrial cancer (1 paper, 2025). Primary or metastatic malignant neoplasm involving the endometrium (mucous membrane that lines the endometrial cavity). "Through our research, the splicing factor SNRPB was found to be overexpressed in patients with endometrial cancer and associated with an unfavorable clinical outcome." (PMID 39910288, 2025). "Here, we propose a potential new strategy for controlling the interaction between POLD1 and PCNA through the splicing factor SNRPB in endometrial cancer cells." (PMID 39910288, 2025). "In this study, we find that silencing the expression of the splicing factor SNRPB decreased POLD1 expression levels in endometrial cancer cells, and POLD1 was identified as a critical downstream target of SNRPB in endometrial cancer cells." (PMID 39910288, 2025). "Our research revealed that the splicing factor SNRPB functions as an oncogenic driver in endometrial cancer." (PMID 39910288, 2025). "The western blotting results further confirmed that the overexpression of miR-654-5p led to a significant decrease in SNRPB protein expression in endometrial cancer cells." (PMID 39910288, 2025). "Low expression of miR-654-5p promoted the overexpression of SNRPB through direct binding to its 3′-UTR in endometrial cancer cells." (PMID 39910288, 2025). "To confirm SNRPB mRNA and protein expression levels in endometrial cancer, we utilized qPCR and western blotting to assess SNRPB expression in fresh-frozen tissues from patients with endometrial cancer and normal endometria." (PMID 39910288, 2025). "Low expression of miR-654-5p contributed to the high expression of SNRPB in endometrial cancer cells through direct binding to the 3′-untranslated region (3′-UTR) of SNRPB." (PMID 39910288, 2025). "In conclusion, these results reveal that downregulation of miR-654-5p contributes to the high expression of SNRPB in endometrial cancer cells through direct binding to its 3′-UTR." (PMID 39910288, 2025). "This study demonstrated elevated expression of the splicing factor SNRPB in endometrial cancer samples." (PMID 39910288, 2025). "The results suggested that SNRPB inhibition decreased POLD1 expression in endometrial cancer cells." (PMID 39910288, 2025). "Hence, targeting the splicing factor SNRPB represents a new strategy for the treatment of endometrial cancer." (PMID 39910288, 2025). "Similarly, immunohistochemical staining revealed that the intensity of SNRPB staining was significantly greater in endometrial cancer tissue than in normal endometrial tissue." (PMID 39910288, 2025). "The oncogenic SNRPB–POLD1 axis is an interesting therapeutic target for endometrial cancer, and antisense oligonucleotide-mediated silencing of SNRPB may constitute a promising therapeutic approach for treating patients with endometrial cancer." (PMID 39910288, 2025). "The results revealed significant overexpression of SNRPB in the endometrial cancer samples." (PMID 39910288, 2025).
gastric cancer (1 paper, 2025). A primary or metastatic malignant neoplasm involving the stomach. "Therefore, SNRPB overexpression is linked to poor prognosis in gastric cancer and is a potential biomarker and therapeutic target." (PMID 41057293, 2025).
head and neck squamous cell carcinoma (1 paper, 2022). A squamous cell carcinoma that arises from any of the following anatomic sites: lip and oral cavity, nasal cavity, paranasal sinuses, pharynx, larynx, and salivary glands. "Only limited protein expression data of SNRPB were available, including BRCA, head and neck squamous cell carcinoma (HNSC), kidney renal clear cell carcinoma (KIRC), LIHC, and OV, and the protein expression level of SNRPB was significantly increased in all five tumors (p < 0.05)." (PMID 36275630, 2022).
lupus (1 paper, 2025). "Four proteins, SNRPB/SNRPN, OGN, IFI27, FBLN2, identified only in extracellular vesicles in the blood of CLE patients were also proteins reported to be related to lupus and inflammation." (PMID 41614843, 2025).
osteosarcoma (1 paper, 2025). A usually aggressive malignant bone-forming mesenchymal neoplasm, predominantly affecting adolescents and young adults. "Therefore, we speculated that WDR3 phase separation-mediated tumorigenesis in osteosarcoma may be associated with the coordinated regulation of SNRPB expression and lysosomal degradation pathways." (PMID 40646517, 2025).
thyroid carcinoma (1 paper, 2022). "Bioinformatics analysis revealed that the expression of SNRPB and cell cycle-associated genes in thyroid carcinoma tissues is positively correlated." (PMID 36329787, 2022).